ST8SIA6 (ST8 alpha-N-acetyl-neuraminide alpha-2,8-sialyltransferase 6)
Description:
Alpha-2,8-sialyltransferase that prefers O-glycans to N-glycans or glycolipids as acceptor substrates. The minimal acceptor substrate is the NeuAc-alpha-2,3(6)-Gal sequence at the non-reducing end of their carbohydrate groups.
Synonyms: SIAT8-F; ST8SiaVI; SIAT8F; SIA8F; ST8SIA-VI
Tractability: Antibody: UniProt predicts a signal peptide or a membrane-spanning region. PROTAC: ubiquitination databases record sites on it.
Gene: Protein-coding gene on chromosome 10 (17,315,421 to 17,454,595, reverse strand). Ensembl gene ENSG00000148488.
Subcellular location: Golgi apparatus membrane
Subcellular location (Human Protein Atlas): Endoplasmic reticulum
Pathways (Reactome):
Metabolism of proteins: N-Glycan antennae elongation; Sialic acid metabolism
Gene Ontology:
Molecular function: alpha-N-acetylneuraminate alpha-2,8-sialyltransferase activity; sialyltransferase activity
Biological process: carbohydrate biosynthetic process; ganglioside biosynthetic process; glycolipid biosynthetic process; glycoprotein metabolic process; N-glycan processing; oligosaccharide metabolic process; protein O-linked glycosylation; glycoprotein biosynthetic process
Cellular component: Golgi membrane
Genetic constraint (gnomAD): Loss-of-function variants: 28 observed, 22.53 expected, observed/expected ratio (o/e) 1.24, 90% interval 0.92 to 1.69. The upper end of that interval is the gene's LOEUF score, 1.69, which puts it in group 6 of 6, group 1 being the genes least tolerant of losing a copy. Missense variants: 387 observed, 390.12 expected, observed/expected ratio (o/e) 0.99, 90% interval 0.91 to 1.08. Synonymous variants: 157 observed, 148.99 expected, observed/expected ratio (o/e) 1.05, 90% interval 0.93 to 1.2.
Homologues: Orthologues: chimpanzee ST8SIA6 (99% identical), macaque ST8SIA6 (90% identical), rabbit ST8SIA6 (87% identical), guinea pig ST8SIA6 (86% identical), mouse St8sia6 (83% identical), pig ST8SIA6 (82% identical), rat St8sia6 (81% identical), dog ST8SIA6 (80% identical), tropical clawed frog st8sia6 (52% identical), zebrafish st8sia6 (36% identical). Paralogues in human: ST8SIA5 (34% identical), ST8SIA1 (34% identical), ST8SIA3 (28% identical), ST8SIA2 (24% identical), ST8SIA4 (23% identical).
Diseases named in the same sentence as ST8SIA6 in open-access papers:
ST8SIA6 is named in the same sentence as 16 diseases in open-access papers, as found by Europe PMC text mining. Sharing a sentence is not in itself a finding about the gene and the disease. The quoted sentences say what the papers report.
colorectal cancer (2 papers, 2023 to 2025). A primary or metastatic malignant neoplasm that affects the colon or rectum. "In this study, we conducted an analysis and screening of potential core pathways, specifically the Glycosphingolipid pathway, and identified four core genes (SMPD1, GLTP, B3GALT4, and ST8SIA6) in colorectal cancer based on data analysis from relevant databases." (PMID 39898245, 2025).
acute myeloid leukemia (1 paper, 2024). Acute myeloid leukemia (AML) is a group of neoplasms arising from precursor cells committed to the myeloid cell-line differentiation. "As upstream regulatory mechanisms controlling miR-5195-3p expression, such as ST8SIA6 in hepatocellular carcinoma, circ_0009910 in acute myeloid leukemia, and circRUNX1 in lung adenocarcinoma have been reported." (PMID 39390599, 2024).
breast carcinoma (1 paper, 2016). "Among these, the expression of ST6GALNAC5, ST8SIA3 and ST8SIA4 was significantly upregulated in breast cancer tissues compared with adjacent tissues, and ST8SIA2 and ST8SIA6 were upregulated in the adjacent tissues." (PMID 28032858, 2016).
colon adenocarcinoma (1 paper, 2022). "The mRNA expression of ST8SIA6 from the UALCAN database was significantly decreased in colon adenocarcinoma (COAD) tissues compared to that in normal tissues." (PMID 35330401, 2022).
colon cancer (1 paper, 2022). "In our study, we demonstrated the correlation between the downregulation of ST8SIA6 and clinicopathological characteristics or the risk of colon cancer from TCGA database." (PMID 35330401, 2022). "In conclusion, this study provides multilevel relationships for the oncogenic roles of ST8SIA6 and its co-expressed genes in colon cancer and its potential as a diagnostic marker for colon cancer." (PMID 35330401, 2022). "In particular, obesity in colon cancer patients has been associated with ST8SIA6 expression." (PMID 35330401, 2022). "We also identified ST8SIA6 co-expression genes in colon cancer using more molecular biology experiments and further clinical research." (PMID 35330401, 2022). "Thus, ST8SIA6 may serve as a potential diagnostic marker for high-grade colon tumors." (PMID 35330401, 2022). "In this study, we explored the involvement of ST8SIA6 in colon cancer using multiple gene databases." (PMID 35330401, 2022). "To investigate the role of ST8SIA6 in colon cancer patients, we evaluated the RNA transcription levels of ST8SIA6 in multiple colon cancer studies from TCGA." (PMID 35330401, 2022). "Our results suggest that ST8SIA6 downregulation in colon cancer is related to multiple biological effects." (PMID 35330401, 2022). "Initially, we demonstrated that ST8SIA6 mRNA levels were significantly decreased in colon cancer tissues compared to normal tissue by analyzing the transcriptome from clinical patient data that was categorized across various subgroups." (PMID 35330401, 2022). "On the TISMO website, different immune checkpoint molecule treatment response groups group analyses showed that the expression of ST8SIA6 with antiPD1 treatment might have a strong immune response in colon cancer." (PMID 35330401, 2022). "Moreover, the biological functions of ST8SIA6 in colon cancer were explored using LinkedOmics and cancer cell metabolism gene DB." (PMID 35330401, 2022). "We further analyzed subgroups based on histological subtypes, disease stages, and nodal metastasis status of TCGA colon cancer samples in the UALCAN database, which showed lower transcriptional levels of ST8SIA6 in colon cancer patients with high-grade patterns than in normal controls." (PMID 35330401, 2022). "It has rarely been determined whether human disease related disialylation is catalyzed by ST8SIA6, and the mechanism of colon cancer progression remains still unknown." (PMID 35330401, 2022). "Finally, we predicted that alterations in the expression of ST8SIA6 in colon cancer are involved in tumor immunity and immunotherapy responses based on transcriptomic analysis." (PMID 35330401, 2022). "Collectively, these results suggest that ST8SIA6 may serve as a novel therapeutic target towards personalized medicine for colon cancer." (PMID 35330401, 2022). "To investigate whether ST8SIA6 expression is correlated with immune infiltration levels in colon cancer, we used the TIMER database." (PMID 35330401, 2022). "However, among the ST8- sialyltransferases, the role of ST8SIA6 in colon cancer remains poorly understood." (PMID 35330401, 2022). "In addition, ST8SIA6 levels affected immunocyte infiltration and immunotherapy responses in colon cancer." (PMID 35330401, 2022). "Thus, ST8SIA6 co-expressed genes and ST8SIA6 may drive multiple oncogenic pathways with abnormal glycosylation in cancer cells and serve as a potential tumor biomarker for colon cancer." (PMID 35330401, 2022). "The findings from unpublished studies demonstrated that the downregulation of ST8SIA6 in COAD tissues from our Biobank promoted cancer stemness and migration in colon cancer by increasing membrane-bound protein levels." (PMID 35330401, 2022). "The relationship between ST8SIA6 expression and tumor stages/grades was investigated by UALCAN analysis, and Kaplan–Meier Plotter analysis was used to analyze the expression of ST8SIA6 on the survival outcome of colon cancer patients." (PMID 35330401, 2022).
colon cancer (continued). "ST8SIA6 downregulation was associated with an advanced stage and poorly differentiated grade; however, ST8SIA6 expression did not affect the survival outcomes in patients with colon cancer." (PMID 35330401, 2022).
rectal adenocarcinoma (1 paper, 2024). "Furthermore, we found that ST8SIA6 levels were positively correlated with CD24 levels in several cancers, including ACC, COAD, HNSC, rectal adenocarcinoma (READ), THCA, KIRP, thymoma (THYM), UCS, CESC, KIRC, and MESO." (PMID 39791710, 2024).
tumor (10 papers, 2017 to 2025). "These networks are associated with ST8SIA6, which affects cancer cell metabolism, invasion, metastasis, tumor-associated microenvironment, and immune infiltration status." (PMID 35330401, 2022). "Furthermore, ST8SIA6 has been linked to the tumor-associated microenvironment and immunotherapy responses." (PMID 35330401, 2022). "Studies show that ST8SIA6 can promote tumour growth in mice by inhibiting immune responses in tumours, characterised by macrophage polarisation toward M2 and upregulation of the immune modulator arginase." (PMID 36077781, 2022). "Targeted interaction disialylation by ST8SIA6 on tumor cells and tumor-infiltrating immune cells is important for cancer immunotherapy." (PMID 35330401, 2022). "In humans, high expression of the ST8SIA6 gene has been attributed an oncogenic function, including tumor cell proliferation, invasion, and migration." (PMID 35630307, 2022). "In a murine model, ST8SIA6 and Siglec-E expression was involved in tumor progression and diabetes by altering macrophage polarization and inflammation status." (PMID 35330401, 2022). "In this study, systematic bioinformatics analysis of global web resources was highly useful for exploring the function of ST8SIA6 in transcriptional alterations, functional networks, and tumor immunity." (PMID 35330401, 2022). "Thus, after immunotherapy, the expression of ST8SIA6 is related to response for immune infiltration and the tumor microenvironment." (PMID 35330401, 2022). "However, the role of ST8SIA6 in tumor immune evasion is currently investigated (grant number: R01-CA243545-01A1)." (PMID 34831278, 2021). "The results showed that the co-localization of ST8SIA6 and CD24 occurred in 4T1 cells and BRCA tumor tissues." (PMID 39791710, 2024). "Next, we detected the interaction between CD24 and ST8SIA6 in 4T1 cells and BRCA tumor tissues using immunofluorescence co-localization." (PMID 39791710, 2024). "Based on the significant alterations in ST8SIA4 and ST8SIA6 expression in the highly invasive FTC cells, we investigated whether these two ST8SIA members could affect the tumour properties of FTC cells." (PMID 28427206, 2017).
cancer (5 papers, 2018 to 2025). A tumor composed of atypical neoplastic, often pleomorphic cells that invade other tissues. "However, ST8SIA6 expression was found to be upregulated in several types of cancer and to be associated with a poor prognosis." (PMID 34975914, 2021). "Moreover, downregulation of ST8SIA6 was positively correlated with cancer recurrence in later stages." (PMID 39898245, 2025). "In addition, we identified the expression of ST8SIA6 in cancer immunotherapy using TISMO database analysis." (PMID 35330401, 2022).
ST8SIA6 also shares sentences with these, for which no sentence is quoted: hepatocellular carcinoma (1 paper); lung adenocarcinoma (1); melanoma (1); neuroblastoma (1); Obesity (1); rectal cancer (1); rectum tumors (1); thymoma (1).